CDKN2A (cyclin dependent kinase inhibitor 2A)
Diseases named in the same sentence as CDKN2A in open-access papers (continued):
Sharing a sentence is not in itself a finding about the gene and the disease.
Lynch syndrome (26 papers, 2015 to 2025). An autosomal dominant hereditary neoplastic syndrome characterized by the development of colorectal carcinoma and a high risk of developing endometrial carcinoma, gastric carcinoma, ovarian carcinoma, renal pelvis carcinoma, and small intestinal carcinoma. "Testing methods that can evaluate variant’s pathogenicity, such as MSI/MMR-IHC for Lynch syndrome, are also required for CDKN2A variants." (PMID 38961426, 2024). "Those with a pathogenic variant in CDKN2A, BRCA2, PALB2, or a Lynch syndrome-associated gene and a first degree relative are potential candidates for screening." (PMID 30186770, 2018). "Similarly to studies on Western populations, mutations in genes other than those associated with the Lynch syndrome, including MUTYH, BRCA2, ATM, BRIP1, CDKN2A, and NF1, were identified." (PMID 39061183, 2024). "No pathogenic variants were observed in BRCA1, STK11, CDKN2A, APC, PRSS1, or those genes associated with Lynch syndrome." (PMID 39594734, 2024).
oral squamous cell carcinoma (26 papers, 2010 to 2025). "The loss of Cyclin-dependent kinase inhibitor 2A (CDKN2A) gene expression has been identified as a mechanism associated with oral squamous cell carcinoma." (PMID 38778403, 2024). "Amplification of CCND1 and deletion of CDKN2A occur in 94% of oral squamous cell carcinoma (OSCC) and structural alterations (homozygous deletion, intra and inter chromosomal fusions) appear to be prominent in CDKN2A." (PMID 37559138, 2023). "Dysregulation of the CDKN2A gene has also been a prominent observation in oral squamous cell carcinoma." (PMID 32025240, 2020). "In 94% of cases of oral squamous cell carcinoma (OSCC), CCND1 amplification and CDKN2A deletion are present; structural alterations in CDKN2A (such as homozygous deletion and intra- and inter-chromosomal fusions) appear to be frequent." (PMID 39199313, 2024). "CDKN2A is one of the MutSig genes with a significantly higher relative frequency of somatic mutations in ML B2 and limited p16INK4A function due to CDKN2A mutation or deletion was associated with perineural invasion in nonsmoking and nondrinking oral squamous cell carcinoma patients." (PMID 37240283, 2023). "Similarly, Zhao found that PLAU, CLDN8 and CDKN2A could predict OS using gene expression profiles of GSE13601, GSE30784, GSE37991 and TCGA in oral squamous cell carcinoma." (PMID 30937621, 2019).
angiosarcoma (25 papers, 2011 to 2024). A malignant tumor arising from the endothelial cells of the blood vessels. "Specifically, we observed a loss in the CDKN2A/B gene on chromosome 16, a gene previously linked to hemangiosarcoma in dogs." (PMID 39872607, 2024). "In our exploration of the genetic landscape of canine hemangiosarcoma, we focused on identifying copy number alterations (CNAs) within genes previously associated with the disease, including CDKN2A/B, VEGFA, KDR, SKI, MYC, and KIT." (PMID 39872607, 2024). "Among the genes historically linked to hemangiosarcoma, alterations in CDKN2A/B, KDR, MYC, and KIT were prominently identified in our study, underscoring their potential roles in the pathogenesis of this cancer in dogs." (PMID 39872607, 2024). "A recent report has shown that use of a lentiviral vector-based system to introduce oncogenic HrasG12V in combination with loss of Cdkn2a via intravenous injection into immune competent mice resulted in the formation of angiosarcomas." (PMID 31221668, 2019). "Furthermore, our CNA analysis identified significant genomic regions linked to hemangiosarcoma pathogenesis, such as alterations in CDKN2A/B, VEGFA, KDR, MYC, and KIT." (PMID 39872607, 2024). "Previous research on DNA methylation in angiosarcoma has focused solely on the tumor suppressor gene cyclin-dependent kinase inhibitor 2A (CDKN2A, or INK4A/ARF)." (PMID 38826780, 2024). "In this regard, it was recently shown that CDKN2A/B was recurrently deleted in canine hemangiosarcoma tumors." (PMID 34946912, 2021). "Compound mutant mice using aP2-Cre to drive recombination resulting in biallelic Dicer1 deletion or the combination of oncogenic KrasG12D activation and Cdkn2a deletion result in angiosarcoma from the transformation of endothelial cells." (PMID 34535684, 2021). "Chromosomal aberrations reported in angiosarcomas include deletions within the CDKN2A locus at chromosome region 9p21, which encodes tumor suppressors p16INK4a, p15INK4b and p14ARF." (PMID 24046386, 2013). "In addition, the in vivo deletion of Cdkn2a in mice lead to the development of lesions which recapitulate human angiosarcoma, however, only 30% of the mice displayed angiosarcomas within 100 days." (PMID 29731980, 2018). "Furthermore, 23% of all tumors in Cdkn2a-null mice have been shown to be angiosarcomas." (PMID 33078209, 2021). "Interestingly, while no developmental vascular defects occur upon Cdkn2a deletion in mice, 23% of all spontaneously formed tumors in these animals were angiosarcomas, suggesting a critical function of this Cdkn gene in maintaining EC homeostasis." (PMID 33078209, 2021).
esophageal cancer (25 papers, 2007 to 2025). A primary or metastatic malignant neoplasm involving the esophagus. "Hypermethylation of CDKN2A exon 2 has been linked to late-stage esophageal cancer, with CDKN2A exon 2 being methylated in eight out of 16 esophageal tumors but in none of 16 normal tissue samples." (PMID 40649906, 2025). "CDKN2A is aberrantly methylated in esophageal cancer, and is associated with metastatic and invasive phenotypes." (PMID 27893424, 2017). "However, the role and diagnostic value of CDKN2A methylation in esophageal cancer (EC) remains controversial." (PMID 28637022, 2017). "In esophageal cancers, CDKN2A, CDKN2B, and CCND1 alterations in the cell cycle pathway were frequently observed." (PMID 38672586, 2024). "For instance, based on DepMap data we observed a significant cooperation between TYMS and CDKN2A in esophageal cancer cell lines." (PMID 34454516, 2021). "Methylation-based markers researches for esophageal cancer have mainly been focused on hypermethylation in promoter region CpG island of numerous tumor suppressor genes, such as APC and CDKN2A, which thus were thought to be potential biomarkers for the diagnosis of BE and esophageal cancer." (PMID 31834866, 2019). "Recently, 40% esophageal cancer samples collected from patients of Meghalaya state having only RAN-chewing habit showed deletion of the microsatellite markers D9S1748 and D9S1749, located close to exon 1β of CDKN2A/ARF gene at 9p21." (PMID 23805780, 2013).
familial atypical multiple mole melanoma syndrome (25 papers, 2006 to 2026). "CDKN2A encodes the p16Ink4a protein and is a major causative gene for familial atypical multiple mole melanoma syndrome (FAMMM), an autosomal dominant syndrome." (PMID 38961426, 2024). "The p16-Leiden founder mutation in the CDKN2A gene is the most common cause of Familial Atypical Multiple Mole Melanoma (FAMMM) syndrome in the Netherlands." (PMID 26111702, 2015). "Development of STS has been described in association with the CDKN2A mutation associated with the familial atypical multiple-mole melanoma syndrome." (PMID 17008869, 2006). "Other variables can influence CDKN2A mutation incidence, and one of these is the presence of atypical moles, like in FAMMM syndrome, which has been linked to CDKN2A-carrier status, since family relatives with this syndrome seem to have a three-fold risk of carrying a germline variant." (PMID 34356093, 2021). "Germline mutations in exon 1α of the p16INK4A/CDKN2A gene are associated with FAMMM syndrome." (PMID 24624093, 2014). "Germline 9p21.3 deletions involving the contiguous CDKN2A/CDKN2B/ANRIL region exhibit cancer predisposition syndrome with characteristics overlapping NF1, familial atypical multiple mole melanoma syndrome (FAMMM), and Li–Fraumeni syndrome (LFS)." (PMID 40046620, 2025). "SNPs within the first haplotype also show association with nevus count, which is of interest given that familial atypical multiple mole melanoma syndrome (FAMMM), a condition characterised by multiple melanocytic nevi, is associated with germline variants in the nearby CDKN2A gene." (PMID 35357426, 2022).
liver cancer (25 papers, 2007 to 2025). An epithelial or non-epithelial malignant neoplasm that arises from the liver. "We also found that 38 somatic cells (10.24%) out of 371 liver cancer samples had mutations and CDKN2A (3%) showed a higher mutation frequency." (PMID 36248822, 2022). "It is commonly believed that activation of the p16 protein in patients with primary liver cancer is related to homozygous deletion and mutation of the CDKN2A gene." (PMID 35154607, 2021). "Initially, it was believed that inactivation of p16 in patients with primary liver cancer is related to homozygous deletions and mutations of CDKN2A gene." (PMID 20569442, 2010). "CDKN2A is highly expressed in various cancer tissues such as liver cancer and kidney cancer and plays an important prognostic role in many cancers." (PMID 36891150, 2023). "The most highly mutated genes, such as MYC, TERT, FASLG, RIPK1, TNFSF10, TARDBP, and CDKN2A, have been well characterized in liver cancer, diffuse large B-cell lymphoma, neuroblastoma, and kidney renal clear cell carcinoma." (PMID 35875102, 2022). "Methylation of the CDKN2A gene has been extensively reported in hepatic cancer patients accompanied by gene methylation in chronic liver disease patients." (PMID 35154607, 2021). "CDKN2A methylation is common in liver cancer and has been reported in 73% of hepatocellular carcinoma tumors." (PMID 26764421, 2016). "We next set out to determine whether MLL3 binding is sufficient to induce transcriptional activation of the CDKN2A locus and, in doing so, extend our analysis to human liver cancer cells." (PMID 37261974, 2023). "Therefore, MLL3 directly binds and co-activates transcription of the CDKN2A locus in human liver cancer cells." (PMID 37261974, 2023). "Recently, studies have shown that the phenomenon of immune infiltration may provide a new perspective on the treatment of liver cancer, and CDKN2A is related to the immune infiltration of HCC." (PMID 34405225, 2021). "In the data on to 371 patients with liver cancer downloaded by TCGA, the patients were divided into CDKN2A high expression (N=232) group and CDKN2A low expression (N=139) group with the median expression of CDKN2A mRNA as the segmentation point (Clinical database sorting from TCGA database)." (PMID 34405225, 2021). "While, in the chronic HBV infection, cancer‐related genes, especially MSCTP1, RASSF1A and CDKN2A, which are reported in liver cancer, are abnormally methylated, suggesting that accumulation of abnormal methylation events has begun in the stage of chronic HBV infection." (PMID 31565863, 2019). "Our study combined genetic, epigenomic, and animal modeling approaches to identify Cdkn2a as an important regulatory target of MLL3 in both mouse and human liver cancers." (PMID 37261974, 2023). "The current results confirm the findings of studies identifying AKT1, CDKN2A, ERBB2, and IL6 as critical markers for metastasis of pancreatic and liver cancers." (PMID 35154607, 2021). "CDKN2A locus is a genomic and transcriptional target of MLL3 in liver cancer." (PMID 37261974, 2023). "Indeed, methylation of CDKN2A was found not only in HCC, but also in patients with chronic liver disease indicating that this finding may be non-specific for liver cancer." (PMID 20569442, 2010).
acute myeloid leukemia (24 papers, 2009 to 2025). Acute myeloid leukemia (AML) is a group of neoplasms arising from precursor cells committed to the myeloid cell-line differentiation. "In a mouse model of acute myeloid leukemia, qPCR analysis of bone marrow cells revealed elevated expression of aging markers Cdkn2a, Cdkn1a, and SASP factors, while the expression of Lmnb1 was reduced." (PMID 39963130, 2025). "HHEX regulates the self-renewal of hematopoietic stem cell (HSC), emergency hematopoiesis, and the initiation of acute myeloid leukemia (AML) via repression of the Cdkn2a tumor suppressor locus." (PMID 33425911, 2020).
ependymoma (24 papers, 2007 to 2025). A WHO grade II, slow growing tumor of children and young adults, usually located intraventricularly. "We also report novel data concerning the clinical meaning of CDKN2A/B loss in ZFTA ependymomas." (PMID 38265522, 2024). "RELA fusions and loss of CDKN2A have been routinely observed in aggressive ependymomas." (PMID 28468611, 2017). "Molecular genetic studies on selected candidate genes revealed frequent NF2 gene mutations in intramedullary spinal ependymomas, while deletions of the CDKN2A gene were frequent in intracranial supratentorial ependymomas but rare in ependymomas from other locations." (PMID 19333441, 2009). "There is another group of supratentorial ependymomas in children that bear the homozygous deletion of CDKN2A." (PMID 40361492, 2025). "Despite the global reduction of H3K27me3, H3K27-altered DMGs and PFA ependymomas retain genomic H3K27me3 to repress gene expression at high-affinity PRC2 sites, including the CDKN2A/B locus encoding the senesce-associated protein p16." (PMID 40556679, 2025). "The methylation of RASSF1A, HIC1 and CDKN2A are the most common epigenetic changes demonstrated in ependymomas." (PMID 34854470, 2022). "Although the DNA methylation analysis revealed unmethylated status for CDKN2A in all ependymoma cases, there are contrasting results in the literature." (PMID 34854470, 2022). "The RASSF1A and CDKN2A genes were selected for analysis in this study since methylations of these genes were previously reported in ependymomas." (PMID 34854470, 2022). "We therefore think that further research is needed in order to address the importance of promoter methylations of CDKN2A in ependymomas." (PMID 34854470, 2022). "The tumors selected for analysis contained many known alterations, including a C11orf95-RELA fusion and CDKN2A alterations in ependymoma tumors (Epe001, Epe002 and Epe003)." (PMID 28468611, 2017). "A certain proportion of high-risk supratentorial ependymomas, including a fraction of ST-EPN-RELA including the EP1NS cells, are known to harbour homozygous deletions of CDKN2A." (PMID 27556362, 2016). "In pediatric ependymomas, CDKN2A deletion coexists with Rela fusion." (PMID 40361492, 2025). "In childhood ependymomas, CDKN2A deletion is restricted to ependymomas with RELA fusion." (PMID 34008056, 2021). "Additionally, ependymomas containing high EZHIP exhibit reduced expression of CDKN2A as compared to ependymomas with low EZHIP." (PMID 31086175, 2019). "For example, the transcriptome of a subgroup of supratentorial ependymoma with amplified EPHB2 and CDKN2A loss (subgroup D) closely matched that of embryonic cerebral Cdkn2a−/− NSCs, whereas spinal ependymomas resembled adult wild-type NSCs from the spinal cord." (PMID 25008045, 2014). "Similarly, we found a 20-fold down-regulation of CDKN2A expression in PFA ependymomas." (PMID 31086175, 2019). "Material and Method: DNA methylation status of CDKN2A, RASSF1A, KLF4 and ZIC2 genes were quantitatively analyzed with pyrosequencing in 44 ependymoma tumor tissues." (PMID 34854470, 2022). "In the present study, we analyzed the gene-specific methylation profiles of the CDKN2A, RASSF1A, KLF4 and ZIC2 genes in the ependymoma tumor tissues." (PMID 34854470, 2022). "Therefore, CDKN2A inactivation in RELA-ependymomas may represent a potential therapeutical target." (PMID 32514758, 2020). "ChIP sequencing tracks show high levels of H3K27me3 at the CDKN2A locus in H3 K27M-containing DIPG and EZHIP-expressing PFA ependymomas." (PMID 31086175, 2019).
ependymoma (continued). "One example is that of ependymomas, which exhibit abnormal profiles of DNA methylation at various genomic loci including RASSF1A; CDKN2A/B and p14 ARF; and MGMT, TIMP3, THBS1 and TP73." (PMID 24212967, 2011). "The tumors suppressor genes RASSF1, CDKN2A, CDKN2B, p14ARF and TP73, as well as other genes potentially involved in the tumorigenesis of ependymomas, such as CASP1, MGMT, TIMP3 and THBS1 are epigenetically silenced by aberrant promoter methylation in subsets of ependymomas." (PMID 19333441, 2009).